RNU6-678P (RNA, U6 small nuclear 678, pseudogene)
Gene: Small nuclear RNA gene on chromosome 3 (133,664,926 to 133,665,034, forward strand). Ensembl gene ENSG00000252641.
Homologues: Orthologues: macaque U6 (91% identical), chimpanzee U6 (88% identical), dog U6 (78% identical), rat LOC120098448 (71% identical), mouse Gm23205 (70% identical), pig U6 (70% identical). Paralogues in human: RNU6-1152P (85% identical), RNU6-211P (83% identical), RNU6-562P (83% identical), RNU6-854P (83% identical), RNU6-16P (83% identical), RNU6-393P (83% identical), RNU6-41P (83% identical), RNU6-643P (83% identical), RNU6-820P (83% identical), RNU6-961P (83% identical), RNU6-1060P (82% identical), RNU6-1181P (82% identical), and 1287 more.